PRL (prolactin)
Diseases named in the same sentence as PRL in open-access papers (continued):
Sharing a sentence is not in itself a finding about the gene and the disease.
itch (2 papers, 2022 to 2023). "First, we showed that the PrL was associated with itch processing using fiber photometry, chemogenetic, optogenetic manipulation, and further behavioral experiments demonstrated the existence of itch-responsive neurons that regulate itch processing in the PrL." (PMID 36619983, 2022). "Taken together, these results suggest that the PrL plays a critical role in the modulation of itch-induced scratching behaviors." (PMID 36619983, 2022). "We also demonstrated the existence of a population of attention-related neurons in the PrL that drive attentional bias to regulate itch processing." (PMID 36619983, 2022). "We further confirmed the effects of PrL neurons inhibition on itch by using optogenetic manipulation." (PMID 36619983, 2022). "Collectively, these results strongly support the conclusion that the PrL plays a critical role in modulating the attentional processing of itch." (PMID 36619983, 2022). "Our study showed that two distinct stimuli which trigger an attentional bias activate overlapping populations of neuron in the PrL and that the PrL plays an important role in the modulation of the attentional distraction from itch." (PMID 36619983, 2022). "In this study, we demonstrated the important regulatory effect of PrL on the attentional processing of itch." (PMID 36619983, 2022). "Inhibition of the PrL, a subregion of the mPFC, reduced both 5-HT- and 48/80-induced itch in rats." (PMID 37553505, 2023). "Thus, in this study, we investigated the potential role of the PrL in regulating the attentional processing of itch." (PMID 36619983, 2022). "Similarly, to explore the roles of itch-related neurons in the PrL in regulating itch processing, we used the same method as above to selectively activate these itch-responsive neurons." (PMID 36619983, 2022).
keratoconus (2 papers, 2010 to 2021). A degenerative, structural disorder of the eye, characterized by a cone-shaped protrusion of the cornea. "Unique proteins more associated with keratoconus included several keratins, immunoglobulins alpha and kappa, precursors to prolactin, lysozyme C, and lipocalin." (PMID 21031023, 2010).
Lipedema (2 papers, 2024 to 2026). Disorder of adipose tissue characterized by symmetric and bilateral enlargement of the lower extremities due to abnormal deposition of subcutaneous fat often in obese women. "The concept of lipedema mimicking a pseudopregnancy hormonal state has been proposed, characterized by increased levels of estrogen, progesterone, prolactin, and relaxin." (PMID 41575573, 2026).
liver cancer (2 papers, 2016 to 2024). An epithelial or non-epithelial malignant neoplasm that arises from the liver. "Recently, a report demonstrating that PRL contributed to the proliferation of liver cancer cells via JAK2 signaling was published." (PMID 27102295, 2016).
liver dysfunction (2 papers, 2021 to 2025). "Given that hormonal disturbances occur in advanced liver dysfunction and that serum prolactin levels increase in CLD, prolactin may serve as a readily available biomarker to assess disease severity and provide prognostic insight." (PMID 39925608, 2025).
lobular adenocarcinoma (2 papers, 2024 to 2025). "Only cumulative exposure duration of ≥5 years to prolactin-increasing antipsychotics was associated with increased odds of both ductal adenocarcinoma (aOR = 1.40, 95% CI = 1.17–1.68) and lobular adenocarcinoma (aOR = 1.65, 95% CI = 1.11–2.45)." (PMID 38687213, 2024). "The odds of both ductal (aOR = 1.40) and lobular adenocarcinoma (aOR = 1.65) were increased after exposure to prolactin-increasing antipsychotics for ≥5 years." (PMID 38687213, 2024).
lung adenocarcinoma (2 papers, 2024 to 2025). A carcinoma that arises from the lung and is characterized by the presence of malignant glandular epithelial cells. "Five hormone levels were significantly associated with lung adenocarcinoma (LUAD): luteinizing hormone, thyroid hormones, insulin, prolactin levels, and parathyroid hormone." (PMID 40017690, 2025). "Univariate Cox regression analysis suggested that the high expression levels of up-regulated DEGs including APOL1, ETFB, KLK8, PPP1R3G, PRL, and SPTA1 were significantly correlated with poorer overall survival (OS) in lung adenocarcinoma." (PMID 38183079, 2024).
lymph node metastases (2 papers, 2010 to 2023). "A retrospective study enrolled 70 MTC patients (28 males and 42 females) without RET genetic testing with the aim of correlating NLR and PRL with lymph node metastasis and recurrence." (PMID 37373942, 2023).
lymphopenia (2 papers, 2006 to 2022). Reduction in the number of lymphocytes. "The study looking at the neuroendocrine stress response found that, in keeping with previous studies, lymphopenia is not related to increased cortisol levels and provided new data on a possible relationship of the low lymphocyte counts with increased prolactin and low leptin levels." (PMID 16859512, 2006).
mammary adenocarcinoma (2 papers, 2007 to 2016). "It is well known that administration of dopaminergic DA2 antagonists is associated with an increase in prolactin, resulting in mammary adenocarcinoma in rodents." (PMID 27790617, 2016). "In chemically induced tumor model, medroxyprogesterone produced mammary adenocarcinoma in balb/c mice possess estrogen and/or progesterone, PRL, and EGF receptors was reported earlier." (PMID 17880731, 2007).
melasma (2 papers, 2025). "Recent network pharmacology and molecular dynamics studies investigating potential melasma treatments have highlighted the involvement of estrogen receptors (ESR1 and ESR2) and the prolactin signaling pathway in melasma pathogenesis." (PMID 41154805, 2025).
Menorrhagia (2 papers, 2012 to 2025). Prolonged and excessive menses at regular intervals in excess of 80 mL or lasting longer than 7 days. "Follicle stimulating hormone, prolactin, oestradiol, and testosterone are potential markers for menorrhagia." (PMID 40356691, 2025). "This study recommends developing a risk assessment tool for menorrhagia in primary healthcare settings, integrating hormonal markers such as FSH (> 10 IU/L), oestradiol outside normal cycle ranges, total testosterone (> 70 ng/dL), and prolactin (> 25 ng/mL)." (PMID 40356691, 2025). "Some women with altered prolactin levels may exhibit compensatory endocrine mechanisms that help maintain normal menstrual function, thereby masking a direct relationship with menorrhagia." (PMID 40356691, 2025). "Elevated levels of FSH, oestrogen, and testosterone, along with reduced prolactin, may serve as potential biomarkers for diagnosing menorrhagia in premenopausal or reproductively aged women." (PMID 40356691, 2025). "Women experiencing menorrhagia had statistically significant increases in levels of FSH (p < 0.0001), oestrogen (p < 0.001), and total testosterone (p < 0.001), while prolactin levels had a statistically significant decrease (p < 0.001) compared to those without menorrhagia." (PMID 40356691, 2025). "The study suggests that levels of FSH, oestrogen, total testosterone, and prolactin differ significantly between women with and without menorrhagia, indicating their potential use in predicting the condition." (PMID 40356691, 2025). "The present findings underscore the complexity of hormonal interactions in menorrhagia and suggests a need for a more nuanced approach to diagnosis and treatment that considers individual patient profiles rather than relying solely on prolactin levels." (PMID 40356691, 2025).
morbid obesity (2 papers, 2021 to 2025). An excess of body weight, normally defined as an individual with a body mass index greater than 35 or a body weight greater than one hundred percent of ideal body weight. "The concentration of prolactin released from adipocytes is lower than that from the pituitary gland, and this additional release of prolactin may influence serum levels in individuals with morbid obesity." (PMID 40650124, 2025).
neuroblastoma (2 papers, 2012 to 2017). Neuroblastoma (NB) is the most common solid, extracranial childhood tumor. "Due to concerns regarding the potential for dopamine to induce an increase in prolactin levels, which can theoretically inhibit T-cell function, dopamine is not the preferred vasopressor for use in patients with high-risk neuroblastoma receiving immunotherapy." (PMID 29900016, 2017).
neuromyelitis optica (2 papers, 2019 to 2025). A rare inflammatory disease of the central nervous system characterized mainly by attacks of uni- or bilateral optic neuritis (ON) and acute myelitis. "Researchers have discovered elevated PRL levels in neuromyelitis optica (NMO) and clinically isolated syndrome (CIS) patients, indicating that altered PRL production is not unique to MS but may be a broader characteristic of autoimmune demyelinating disorders." (PMID 41476991, 2025). "Patients with MS have higher PRL levels compared to controls, and this has also been shown in patients with neuromyelitis optica (NMO)." (PMID 31847209, 2019).
neuropathic pain (2 papers, 2020 to 2022). Chronic pain caused by damage to nerve fibers. "Optogenetic inhibition of the PrL, or one of its projection targets, the nucleus accumbens, augments sensory and affective symptoms of acute pain, and also increases nociceptive sensitivity and aversive responses in neuropathic pain models." (PMID 32414089, 2020).
parathyroid tumors (2 papers, 2012 to 2015). "In in vitro studies of short-term cultured human parathyroid tumour cells, prolactin stimulation was associated with significant transcriptional changes in JAK/STAT, RIG-I like receptor and type II interferon signalling pathways as documented by gene expression profiling." (PMID 22606260, 2012). "Comparative gene expression profiling was done using the Affymetrix platform analysing parathyroid tumour cells treated with 200 μg/L prolactin as compared to untreated controls." (PMID 22606260, 2012). "A possible effect on PTH secretion from prolactin stimulation of short-term cultured parathyroid tumour cells was studied by parallel perifusion at two different prolactin concentrations (100 or 200 μg/L)." (PMID 22606260, 2012). "We determined PRLR gene and PRLr isoform expression in parathyroid tumours and normal tissues, and evaluated parathyroid tumour cell function and expression profiles upon prolactin stimulation in vitro." (PMID 22606260, 2012).
personality disorder (2 papers, 2008 to 2025). A diverse category of psychiatric disorders characterized by behavior that deviates markedly from the expectations of the individual's culture; this pattern of deviation is pervasive and inflexible and is stable over time. "Impulsive aggressive patients with personality disorder show blunted prolactin release after administration of fenfluramine, which suggests a hyposensitive 5-HT system." (PMID 19014547, 2008).
phaeochromocytoma (2 papers, 2022 to 2024). "Germline mutations in SDHA, SDHB, SDHC, and SDHD (collectively, SDHx) are associated with the development of PRL- and GH-secreting adenomas, pheochromocytomas, and/or paragangliomas, a syndrome named 3P association." (PMID 35743266, 2022).
pituitary deficiencies (2 papers, 2020 to 2025). "Z-scores of cognitive tests were not correlated to prolactin at diagnosis, duration of biochemical control/remission, presence of pituitary deficiencies, or total HADS scores." (PMID 40512752, 2025).
premature ovarian failure (2 papers, 2009 to 2016). "Whereas mice expressing PRL-RS display early follicular recruitment followed by severe follicular death and premature ovarian failure, overexpression of PRL-RS rescues the mammopoiesis defect in heterozygous PRLR knockout mice." (PMID 19703295, 2009). "We have recently shown that in mice expressing only PRL-RS, PRL represses the expression of GALT and causes premature ovarian failure and non-apoptotic cell death, similar to the pathology seen in women with the GALT mutation." (PMID 19703295, 2009).
prion disease (2 papers, 2020 to 2025). A transmissible disease that is caused by a protein that is able to induce abnormal folding of normal cellular proteins, leading to characteristic spongiform brain changes, which are associated with neuronal loss without an inflammatory response. "GalCer treatment altered pathways of long-term potentiation/depression, estrogen signaling, synaptic vesicle cycle, ErbB signaling, and prion diseases in males, but prolactin signaling, selenium compound metabolism and steroid biosynthesis in females." (PMID 33006978, 2020).
psoriasis plaques (2 papers, 2014 to 2024). "Among the effects of prolactin that favour the appearance of psoriasis plaques are the stimulation of IL-17 production by keratinocytes, recruitment of T lymphocytes at the skin level and stimulation of angiogenesis and IFN gamma production by inflammatory cells." (PMID 38399624, 2024).
respiratory distress syndrome (2 papers, 2019 to 2022). "Some studies have also found that new-borns with lower levels of prolactin in cord blood have an increased risk of respiratory distress syndrome than new-borns with higher levels of prolactin." (PMID 35757428, 2022).
selenium deficiency (2 papers, 2012 to 2021). A nutritional deficiency disease resulting from inadequate selenium levels in the body, which can lead to impaired function of selenoproteins essential for antioxidant defense and thyroid hormone metabolism. "• In patients with PCM, abnormal immune response to pregnancy, increased myocyte apoptosis, selenium deficiency, cultural practices such as those of the Zaria women, and prolactin excess/cleavage are other causes that have been advanced by workers in the field." (PMID 23192260, 2012).
seminoma (2 papers, 2023 to 2025). A radiosensitive malignant germ cell tumor found in the testis (especially undescended), and extragonadal sites (anterior mediastinum and pineal gland). "Among pituitary hormone genes, GNRH1 (weak effect), PRL and CGA (strong effect) were expressed at significantly higher levels in NSGCT than seminoma samples." (PMID 37669975, 2023).
sicca syndrome (2 papers, 2015 to 2021). "It should be noted that patients with Sjögren's syndrome have eye dryness and high serum levels of prolactin 10, but most cases occur without the typical signs of Sjögren's syndrome." (PMID 26375566, 2015).
Sleep apnea (2 papers, 2021 to 2025). An intermittent cessation of airflow at the mouth and nose during sleep is known as sleep apnea. "Most patients with sleep apnea show elevated levels of prolactin, while low prolactin has been associated with a higher risk for PPD." (PMID 39997651, 2025). "This may indicate that in the hPRL group the effect of sleep disordered breathing, one of the leading causes of EDS, might be less important and that other factors might be playing a key role, such as increased PRL." (PMID 34942875, 2021). "However, based on what we have observed, it seems that PRL might really be associated to EDS, regardless of the concomitant presence of sleep-disordered breathing and hypoxemia." (PMID 34942875, 2021).
spinal muscular atrophy (2 papers, 2016 to 2025). A motor neuron disease that affect the muscles, and characterized by muscle weakness and atrophy resulting from progressive degeneration and irreversible loss of the anterior horn cells in the spinal cord (i.e., lower motor neurons) and the brain stem nuclei. "PRL has been indicated as a promising therapeutic agent for spinal muscular atrophy (SMA), a neurodegenerative disorder characterized by the loss of motoneurons and progressive muscular atrophy." (PMID 27918427, 2016).
substance abuse (2 papers, 2014 to 2021). The use of a drug for a reason other than which it was intended or in a manner or in quantities other than directed. "First, genetic variations in prolactin lead to an exaggerated prolactin response to stress, which may further be modulated by childhood adversity or possibly by substance abuse." (PMID 24800074, 2014).
thrombophilia (2 papers, 2017 to 2021). A condition characterized by an abnormally high level of thrombi. "Only after euploid results further diagnostic procedures like parental genetics, hysterosalpingography, thrombophilia, thyroid function, HbA1c and Prolactin-testing should be performed according to American guidelines." (PMID 33211176, 2021).
thymic atrophy (2 papers, 2013 to 2021). "Researchers confirm that systematic prolactin impairment during infection increases the level of glucocorticoid, leading to thymic atrophy." (PMID 34113341, 2021). "Since PRL seems to protect from GC-induced thymic atrophy during acute infection, together withthe fact that its depletion worsened the course of disease, we decided to evaluate the effect of PRLre-establishment in T. cruzi-infected mice." (PMID 24324845, 2013). "In the last set of experiments, we checked if the reestablishment of PRL systemic levels couldprevent T. cruzi-induced thymic atrophy." (PMID 24324845, 2013). "Considering theimmunomodulatory role of PRL upon the effects caused by GC, we investigated if intrathymiccross-talk between GC and PRL receptors (GR and PRLR, respectively) might influence T.cruzi-induced thymic atrophy." (PMID 24324845, 2013).
thyrotoxicosis (2 papers, 2016 to 2024). A hypermetabolic syndrome caused by the elevation of thyroid hormone levels in the serum. "Individuals who have symptoms of thyrotoxicosis, neurological manifestations indicative of optic chiasm compression, and observed co-hypersecretion of additional anterior pituitary hormones, such as prolactin or GH, are more likely to have a TSH-secreting pituitary macroadenoma." (PMID 39091608, 2024).
transient ischemic attack (2 papers, 2020 to 2022). A brief attack (from a few minutes to an hour) of cerebral dysfunction of vascular origin, with no persistent neurological deficit. "Transient ischemic attack increased PRL concentrations and increased plasma PRL levels were significantly linked with platelet P-selectin." (PMID 36569944, 2022).
ZIKV infection (2 papers, 2020). "Interestingly, immune escape by ZIKV infection could be caused by downregulation of prolactin signaling including IRS2, PIK3C3, JAK3, STAT3, and IRF1 as well as mitochondria dysfunction and oxidative phosphorylation in myeloid dendritic cells." (PMID 32287277, 2020). "Interestingly, “Prolactin Signaling” was downregulated in mDC by ZIKV infection, but not in neuronal cells." (PMID 32287277, 2020).
Zinc deficiency (2 papers, 2009 to 2019). A deficiency of the essential metal Zinc; an essential cofactor for many enzymes. "Zinc deficiency alters the circulating levels of a number of hormones associated with the onset of labor such as progesterone and prolactin." (PMID 31390765, 2019).
adrenocortical insufficiency (1 paper, 2024). An endocrine or hormonal disorder that occurs when the adrenal cortex does not produce enough of the hormone cortisol and in some cases, the hormone aldosterone. "Secondary adrenocortical insufficiency, growth hormone deficiency, delayed gonadotropin response, and elevated prolactin levels were also observed." (PMID 38769570, 2024).
Alkalosis (1 paper, 2019). Depletion of acid or accumulation base in the body fluids. "Considering the proven alkalotic effect of the dose used and protocol of administration of CIT, our findings suggest that orally induced metabolic alkalosis did not affect serum PRL response to TT in the heat." (PMID 31013820, 2019).
anaphylaxis (1 paper, 2021). An acute hypersensitivity reaction that occurs from exposure to an allergen. "Changing levels of progesterone and/or prolactin were also suggested as possible predisposing factors in breastfeeding induced anaphylaxis, sometimes in association with the administration of nonsteroidal anti-inflammatory drugs, which are potential non-IgE-mediated anaphylaxis triggers." (PMID 34575019, 2021).